GOLM1 (golgi membrane protein 1)
Diseases named in the same sentence as GOLM1 in open-access papers (continued):
Sharing a sentence is not in itself a finding about the gene and the disease.
Hepatitis (14 papers, 2014 to 2026). Inflammation of the liver. "In 2000, a novel protein named Golgi phosphoprotein 73 (GP73, also termed as GOLM1 or GOLPH2) was identified and isolated from the liver of a patient who suffered from adult giant-cell hepatitis (GCH), a rare form of hepatitis with presumed viral etiology." (PMID 34950590, 2021).
lung cancer (12 papers, 2013 to 2025). A malignant neoplasm involving the lung. "Through data mining in TCGA, we found that GOLM1 is associated with lung cancer, especially lung adenocarcinoma, and the expression level of GOLM1 is causally related to overall survival." (PMID 33649292, 2021). "Recently, Song Q and collaborators employed a global phosphoproteomics approach to acquire further insights into the signaling pathways regulated by GOLM1 responsible for promoting lung cancer malignancy." (PMID 35805075, 2022). "Following the cell scratch test, transwell cell invasion assay and transwell cell migration assay, we proved overexpression of GOLM1 facilitated migration and invasion of lung cancer cells in vitro." (PMID 33649292, 2021). "High correlation between lung cancer and upregulation of GOLM1 expression were confirmed in this study." (PMID 33649292, 2021). "In our research, we confirmed the conclusion drawn by previous studies that GOLM1 is overexpressed in lung cancer." (PMID 33649292, 2021). "Upregulation of GOLM1 markedly improved cell proliferation, migration, and invasion in the lung cancer cell line, PC9, and PC9 xenografts in nude mice." (PMID 33649292, 2021). "To sum up, combined our cellular assays and animal trials, we demonstrated that overexpression of GOLM1 facilitating lung cancer progression as an indispensable factor." (PMID 33649292, 2021). "Therefore, agents that affect GOLM1 directly or downstream of GOLM1 activity can potentially be used in patients with lung cancers that show high expression of GOLM1." (PMID 33649292, 2021). "GOLM1 as a critical oncogene facilitates lung cancer cell proliferation, migration and invasion." (PMID 33649292, 2021). "Golm1 is increased in adenocarcinoma tissues as well as in serum of lung cancer patients." (PMID 34464420, 2021). "In this study, we showed that GOLM1 may have a vital role in the progression of lung cancer because we observed the overexpression of GOLM1 in all tumor tissues acquired from surgery." (PMID 33649292, 2021). "However, more studies are needed to reveal the role of GOLM1 in lung cancer." (PMID 33649292, 2021). "However, Phosphoproteome landscapes of GOLM1 overexpression in lung cancer remain largely unknown." (PMID 33649292, 2021). "The mechanisms by which GOLM1 is involved in lung cancer have not been clarified." (PMID 33649292, 2021). "Lung cancer also has high expression profile of GCNT3 (a gene regulating mucin synthesis), GOLM1(a gene coding for a Golgi transmembrane protein) and IGF2BP3 (a gene coding for a RNA binding protein), which are all positively correlated with malignant progression of lung cancer." (PMID 33129284, 2020).
giant-cell hepatitis (10 papers, 2008 to 2024). "GP73, encoded by the GOLM1 gene, was first identified in liver tissues derived from patients with adult giant-cell hepatitis (GCH)." (PMID 39845976, 2024). "GOLPH2 is a 73-kDa Golgi apparatus-associated protein coded by the gene GOLM1 located on chromosome 9q21.33 and was originally cloned from a library derived from liver tissue of a patient with adult giant-cell hepatitis." (PMID 18781151, 2008). "GOLPH2 protein is coded by the GOLM1 gene on chromosome 9q21.33 and was first described in giant-cell hepatitis." (PMID 20184749, 2010).
lung adenocarcinoma (9 papers, 2013 to 2025). A carcinoma that arises from the lung and is characterized by the presence of malignant glandular epithelial cells. "In lung adenocarcinoma, it inhibits tumor growth by targeting the GOLM1/JAK-STAT pathway, while in myoblasts, it promotes differentiation by suppressing proliferation." (PMID 40282014, 2025). "In lung adenocarcinoma, GOLM1 facilitates cell proliferation and represents unfavorable survival." (PMID 32781986, 2020). "We found that GOLM1 expression in both lung adenocarcinoma and lung squamous cell carcinoma was significantly higher than that in the normal control group, and the different level in lung adenocarcinoma was statistically significantly higher than that in lung squamous cell carcinoma." (PMID 33649292, 2021).
melanoma (7 papers, 2016 to 2024). A malignant, usually aggressive tumor composed of atypical, neoplastic melanocytes. "GOLM1 is also implicated in other cancers, including melanoma and colon cancer." (PMID 38601164, 2024). "This may suggest that comparable to GOLM1 Ser307Leu, the ATM Ser49Cys variant is associated with a lower risk of melanoma and/or a later age of onset." (PMID 38338943, 2024). "ATM Ser49Cys, GOLM1 Ser307Leu and MITF Glu318Lys all occur in higher frequencies in melanoma-affected populations (2.3%, 2.9% and 1.6–2.8%, respectively) as compared to general populations (~0.2% and 0.6–0.8%, respectively)." (PMID 38338943, 2024).
bladder cancer (5 papers, 2018 to 2022). "Some previous researchers have elaborated on the connection between GOLM1 and the TGF-β1/Smad2 signaling pathway in bladder cancer and HCC." (PMID 36499755, 2022).
glioblastoma (5 papers, 2020 to 2024). The most malignant astrocytic tumor (WHO grade IV). "GOLM1’s effect via the Wnt/β-catenin signaling pathway has also been shown in human glioblastoma, which can promote its proliferation and motility." (PMID 36499755, 2022). "GOLM1 modulates glioblastoma cell migration, invasion and EMT by regulating the Wnt/β-catenin signaling cascade." (PMID 35805075, 2022). "Previously, downregulation of GOLM1 inhibits glioblastoma cell proliferation and motility, and progression." (PMID 32781986, 2020). "In addition, GOLM1 promotes glioblastoma cell proliferation by facilitating the Wnt signaling pathway, as described in the previous section." (PMID 35805075, 2022).
colon cancer (4 papers, 2021 to 2024). "GOLM1 deficiency in mice conferred susceptibility to mucosal inflammation and colitis-induced epithelial damage, which consequently promoted colon cancer." (PMID 33850109, 2021). "In this study, we first analyzed the expression of GOLM1 in patients’ tissues to investigate whether GOLM1 was potentially implicated in the pathogenesis of colitis and colon cancer." (PMID 33850109, 2021). "Therefore, GOLM1 involves in maintaining intestinal homeostasis and suppressing colon cancer carcinogenesis." (PMID 33850109, 2021). "To investigate the role of GOLM1 in colon cancer, we established AOM/DSS-induced CAC model in systemic Golm1 knockout (Golm1−/−) mice and control mice (WT)." (PMID 33850109, 2021).
colorectal cancer (4 papers, 2021 to 2024). A primary or metastatic malignant neoplasm that affects the colon or rectum. "However, GOLM1 also maintains the homeostasis of intestinal epithelial cells by regulating the Notch signaling pathway, protecting the intestine from damage caused by colitis and colorectal cancer." (PMID 38997719, 2024). "Previous research has shown that abnormal regulation of GOLM1 plays a significant role in the development and metastasis of colorectal cancer, potentially promoting tumor immune evasion and metastasis by recruiting myeloid-derived suppressor cells." (PMID 38997719, 2024). "However, the function and biological function of GOLM1 in human colorectal cancer needs further research." (PMID 34729117, 2021).
glioma (4 papers, 2017 to 2022). A benign or malignant brain and spinal cord tumor that arises from glial cells (astrocytes, oligodendrocytes, ependymal cells). "To illuminate the mechanisms underlying GOLM1 promotion in the development of human glioma, we used an antibody array to examine the phosphorylation status of 43 human phospho-kinases in lysates prepared from U251-NC and -sh-GOLM1 cells." (PMID 29282077, 2017). "Functional assays in glioma cell lines confirmed this association and illuminated a potential role for GOLM1 in PDGFRα signaling." (PMID 29282077, 2017). "Based on these findings, we investigated the function of GOLM1 in glioma and found that it was significantly associated with glioma invasion and migration, as well as proliferation." (PMID 29282077, 2017). "Here, we examined the role of GOLM1 in the development of human glioma and its functional relationship with PDGFRα." (PMID 29282077, 2017). "In summary, GOLM1 facilitates proliferation, invasion, and migration of human glioma cell lines potentially through the activation of AKT." (PMID 29282077, 2017). "GOLM1 was also increased in glioma cell lines compared to NHA based on qRT-PCR and western blot analysis." (PMID 29282077, 2017). "Although we found that GOLM1 accelerates glioma progression through activation of AKT and its downstream effectors, our study has not fully illuminated the precise function of GOLM1 in AKT-related molecular networks." (PMID 29282077, 2017). "To investigate the functional relationship between PDGFRα and GOLM1, we examined GOLM1 protein levels in parental and modified glioma cells treated with PDGFA." (PMID 29282077, 2017). "Silencing of GOLM1 also decreased volume and weight of tumor mass implanted subcutaneously, which further confirmed the inhibition of GOLM1 on glioma growth." (PMID 29282077, 2017). "IHC staining for the proliferation marker Ki-67 further confirmed an oncogenic role for GOLM1 in glioma." (PMID 29282077, 2017). "PDGFA/PDGFRα-regulated GOLM1 promotes glioma progression possibly through activation of a key signaling kinase, AKT." (PMID 29282077, 2017). "GOLM1 was highly expressed (scores ≥3) in 9/20 low grade gliomas (LGG; 45.0%) and 40/49 high grade gliomas (HGG; 81.6%) whereas GOLM1 was nearly undetectable in non-neoplastic brain tissue samples (n = 6)." (PMID 29282077, 2017). "Based on previous studies, we examined the role of GOLM1 in the proliferation, invasion, and migration of glioma cell lines and observed that the protein promotes these properties in glioma, not only in vitro but also in vivo." (PMID 29282077, 2017). "To investigate the function of GOLM1 in glioma, we first examined levels of GOLM1 mRNA in primary human gliomas (WHO grade II, n = 8; WHO grade IV, n = 8)." (PMID 29282077, 2017). "Based on the increased expression of GOLM1 in U251 and A172 cell lines relative to U87MG cells, knockdown experiments were performed in these cells to investigate the impact of the loss of function of GOLM1 in the development of human glioma." (PMID 29282077, 2017). "Here, we examined the role of GOLM1 in the development of human glioma." (PMID 29282077, 2017). "Finally, to examine the impact of increased GOLM1 expression on glioma cell invasion and growth in vivo, modified U87MG cells were orthotopically implanted in nude mice." (PMID 29282077, 2017). "Furthermore, we demonstrated that PDGFA/ PDGFRα upregulates GOLM1, and that GOLM1 acts as a key component in PDGFA/ PDGFRα-mediated glioma progression." (PMID 29282077, 2017). "In this work, we identified GOLM1 as a potential target of glioma molecular therapy." (PMID 29282077, 2017). "Therefore, we identified GOLM1 as a potential oncogene in the development of human glioma and target in the treatment of the disease." (PMID 29282077, 2017). "Therefore, we examined whether phosphorylation of AKT and ERK might mediate GOLM1-induced proliferation, invasion, and migration in glioma." (PMID 29282077, 2017).
glioma (continued). "Furthermore, we found that AKT activation was the key element in GOLM1-induced glioma progression." (PMID 29282077, 2017). "Therefore, GOLM1 knockdown on migration and invasion of glioma cells were investigated." (PMID 29282077, 2017). "GOLM1 interference may therefore provide a novel therapeutic target and improve the efficacy of glioma treatment, particularly in the case of the proneural molecular subtype of human glioma." (PMID 29282077, 2017). "Inhibition of miR-384 activity induced autophagy by putatively interfering with Golgi membrane protein 1 (GOLM1) and led to increased migration and invasion of glioma cells." (PMID 34322395, 2021). "The last finding of this research belongs to the regulation of PDGFA/PDGFRα on GOLM1, while GOLM1 was also a key element of PDGFA/PDGFRα-mediated activation of AKT, as well as the progression of glioma cells." (PMID 29282077, 2017). "To examine the role of GOLM1 overexpression in human glioma development, we used U87MG cells which exhibited GOLM1 protein levels similar to NHA." (PMID 29282077, 2017). "Silencing of GOLM1 attenuated proliferation, migration, and invasion of U251, A172 and P3#GBM (primary glioma) cells, while overexpression of GOLM1 enhanced malignant behavior of U87MG cells." (PMID 29282077, 2017). "Similarly, GOLM1 promotes PDGFA/PDGFRα-mediated migration and invasion of glioma through the activation of PI3K/AKT/mTOR cascade, which, in turn, induces the activation of GSK3β and the increased expression of ZEB1 and Snail." (PMID 35805075, 2022). "This newly discovered lncRNA MALAT1/miR-384/GOLM1 axis may provide new insights into the mechanisms of glioma metastasis, and lncRNA MALAT1 may be a promising target for future glioma therapy." (PMID 33029125, 2020). "Besides, GOLM1, a downstream target of miR-384, was also identified to promote autophagy by activating protein kinase AKT, suggesting that lncRNA MALAT1, as a miR-384 sponge, promoted vesicle nucleation and thus enhanced glioma migration and invasion by upregulating GOLM1." (PMID 33029125, 2020). "Levels of GOLM1 were elevated in human gliomas, especially in WHO grade IV gliomas (~ 5–7×), when compared to non-neoplastic brain tissue samples (n = 4)." (PMID 29282077, 2017).
pancreatic cancer (4 papers, 2015 to 2024). "Regarding GOLM1, 1 study supported that long noncoding RNA TP73-AS1 could promote pancreatic cancer progression through GOLM1 upregulation by competitively binding to miR-128–3p." (PMID 38608280, 2024).
lymph node metastasis (3 papers, 2021). "We found that the elevated GOLM1 expression was positively associated with tumor invasion, lymph node metastasis and AJCC stage." (PMID 34729117, 2021).
colitis (2 papers, 2021 to 2024). Inflammation of the colon. "Of clinical relevance is that GOLM1 deficiency-mediated robust colitis, pro-tumorigenic inflammation, and CAC can be alleviated by either probiotic agents, mucosal safeguard or Notch signaling blockade." (PMID 33850109, 2021). "All Golm1−/− mice treated with 3% DSS succumbed to colitis 14 days after DSS induction while >80% of their WT counterparts survived." (PMID 33850109, 2021). "We then generated systemic and epithelial-specific Golm1 knockout mice as well as bone marrow chimera transplantation models to determine the involvement of GOLM1 in colitis and CAC." (PMID 33850109, 2021). "In summary, by revealing the role of GOLM1 in maintaining intestinal homeostasis to restrict colitis and colonic tumorigenesis, we demonstrate that GOLM1 exerts suppressive function on carcinogenesis distinct from its previously recognized oncogenic effect on liver, prostate, and lung malignancies." (PMID 33850109, 2021). "Colitis-associated pathology observed in Golm1−/− mice is thus mainly due to GOLM1 deficiency in non-hematopoietic cells." (PMID 33850109, 2021). "To understand the mechanisms involved in the colitis and CAC vulnerability of Golm1−/− mice, we differentiated the contributions of hematopoietic cells from those of non-hematopoietic cells in colitis progression in Golm1−/−mice with bone marrow chimera transplantation." (PMID 33850109, 2021). "Therefore, GOLM1 maintains IEC homeostasis and protects against colitis and colon tumorigenesis by modulating the equilibrium of Notch signaling pathway." (PMID 33850109, 2021).
diabetes (2 papers, 2025). "Podocyte-specific GOLM1 ablation prevents, while podocyte-specific GOLM1 overexpression facilitates diabetes-related inflammation, oxidative damage, apoptosis, and renal dysfunction in vivo and in vitro." (PMID 40652516, 2025).
dysplasia (2 papers, 2013 to 2021). A usually neoplastic transformation of the cell, associated with altered architectural tissue patterns. "Histological analysis of the tumor-bearing colons revealed more low-grade and high-grade dysplasia in AOM/DSS-treated Golm1−/− mice, suggesting that GOLM1 deficiency increased mouse susceptibility to CAC." (PMID 33850109, 2021).
metastatic cancer (2 papers, 2021 to 2025). A carcinoma which has spread from the original site of growth to another anatomic site. "As previously reported, GOLM1 has been identified as a leading gene associated with cancer metastasis; it is supposed that GP73 serves as a potential drug target in therapeutics of metastatic cancers." (PMID 34950590, 2021).
prostate tumor (2 papers, 2020 to 2021). "Despite previously reported miRNAs targeting GOLM1 such as miR-382, miR-145, miR-200a, we first identified miR-3935 as the upstream regulator of GOLM1 in prostate tumor." (PMID 32781986, 2020). "Compared to normal tissues, ARHGEF38, NETO2, GOLM1, and SAPCD2 were hypomethylated in prostate tumors, while PRSS21 was hypermethylated in prostate tumors compared, which may be the underlying mechanism for the abnormal expression of the five genes in PCa." (PMID 34540835, 2021).
pulmonary fibrosis (2 papers, 2024 to 2025). Chronic progressive interstitial lung disorder characterized by the replacement of the lung tissue by connective tissue, leading to progressive dyspnea, respiratory failure, or right heart failure. "According to the literature, GOLM1 can upregulate NEAT1 to promote pulmonary fibrosis, which is a major characteristic of BPD, before the implementation of antenatal steroids and surfactant therapy." (PMID 40098026, 2025).
colonic disorder (1 paper, 2021). Pathological processes in the colon region of the large intestine (intestine, large). "Lastly, we alleviated GOLM1 depletion-mediated colonic disorder by targeting the GOLM1-Notch signaling cascades we dissected." (PMID 33850109, 2021).
Crohn disease (1 paper, 2024). A gastrointestinal disorder characterized by chronic inflammation involving all layers of the intestinal wall, noncaseating granulomas affecting the intestinal wall and regional lymph nodes, and transmural fibrosis. "In Crohn's disease, there is abnormal interaction between microbiota and host proteins such as GOLM1, which may be related to the development of intestinal inflammation and bacterial translocation." (PMID 38997719, 2024).
migraine (1 paper, 2025). "Six proteins were significantly upregulated in migraine with a >1.5 fold change compared to controls and Padj < 0.05 (FAM3C, GOLM1, PSA7, ENPP2, DSG2, TFRC); 3 proteins were significantly downregulated (FGL1, CAH2, AMYP)." (PMID 40852402, 2025).